HSALR1 (HSP90AB1 associated lncRNA 1)
Gene: Long non-coding RNA gene on chromosome 16 (88,731,180 to 88,741,425, forward strand). Ensembl gene ENSG00000224888.
Diseases named in the same sentence as HSALR1 in open-access papers:
HSALR1 is named in the same sentence as 1 disease in open-access papers, as found by Europe PMC text mining. Sharing a sentence is not in itself a finding about the gene and the disease. The quoted sentences say what the papers report.
chronic obstructive pulmonary disease (1 paper, 2023). A chronic and progressive lung disorder characterized by the loss of elasticity of the bronchial tree and the air sacs, destruction of the air sacs wall, thickening of the bronchial wall, and mucous accumulation in the bronchial tree. "The study provides the evidence that a novel lncRNA HSALR1 is highly expressed in chronic obstructive pulmonary disease and is associated with human bronchial fibroblasts proliferation." (PMID 37317677, 2023).